GRB10 (growth factor receptor bound protein 10)
Description:
Adapter protein which modulates coupling of a number of cell surface receptor kinases with specific signaling pathways. Binds to, and suppress signals from, activated receptors tyrosine kinases, including the insulin (INSR) and insulin-like growth factor (IGF1R) receptors. The inhibitory effect can be achieved by 2 mechanisms: interference with the signaling pathway and increased receptor degradation. Delays and reduces AKT1 phosphorylation in response to insulin stimulation. Blocks association between INSR and IRS1 and IRS2 and prevents insulin-stimulated IRS1 and IRS2 tyrosine phosphorylation. Recruits NEDD4 to IGF1R, leading to IGF1R ubiquitination, increased internalization and degradation by both the proteasomal and lysosomal pathways. May play a role in mediating insulin-stimulated ubiquitination of INSR, leading to proteasomal degradation. Negatively regulates Wnt signaling by interacting with LRP6 intracellular portion and interfering with the binding of AXIN1 to LRP6. Positive regulator of the KDR/VEGFR-2 signaling pathway. May inhibit NEDD4-mediated degradation of KDR/VEGFR-2.
Synonyms: GRB-IR; Grb-10; IRBP; MEG1; RSS
Tractability: Small molecule: it has a high-quality binding pocket. Antibody: its Gene Ontology location is reachable by antibodies, with high confidence. PROTAC: ubiquitination databases record sites on it; its protein half-life has been measured.
Gene: Protein-coding gene on chromosome 7 (50,590,063 to 50,793,462, reverse strand). Ensembl gene ENSG00000106070.
Subcellular location: Cytoplasm
Subcellular location (Human Protein Atlas): Vesicles
Pathways (Reactome):
Signal Transduction: IRS activation; Insulin receptor signalling cascade; Signal attenuation; Signaling by SCF-KIT
Cellular responses to stimuli: Response of EIF2AK1 (HRI) to heme deficiency
Developmental Biology: RET signaling
Immune System: FLT3 Signaling
Gene Ontology:
Molecular function: protein binding; insulin receptor binding; signaling receptor complex adaptor activity; protein-macromolecule adaptor activity
Biological process: negative regulation of Wnt signaling pathway; positive regulation of vascular endothelial growth factor receptor signaling pathway; insulin receptor signaling pathway; intracellular signal transduction; negative regulation of D-glucose import; negative regulation of insulin receptor signaling pathway; positive regulation of cold-induced thermogenesis; signal transduction
Cellular component: protein-containing complex; cytoplasm; cytosol; plasma membrane
Genetic constraint (gnomAD): Loss-of-function variants: 18 observed, 73.12 expected, observed/expected ratio (o/e) 0.25, 90% interval 0.17 to 0.37. The upper end of that interval is the gene's LOEUF score, 0.37, which puts it in group 1 of 6, group 1 being the genes least tolerant of losing a copy. Missense variants: 523 observed, 708.61 expected, observed/expected ratio (o/e) 0.74, 90% interval 0.69 to 0.79. Synonymous variants: 272 observed, 283.58 expected, observed/expected ratio (o/e) 0.96, 90% interval 0.87 to 1.06.
Homologues: Orthologues: chimpanzee GRB10 (99% identical), macaque GRB10 (93% identical), dog GRB10 (90% identical), pig GRB10 (90% identical), rabbit GRB10 (83% identical), rat Grb10 (81% identical), tropical clawed frog grb10 (81% identical), mouse Grb10 (78% identical), guinea pig GRB10 (75% identical), zebrafish grb10b (75% identical), zebrafish grb10a (72% identical), Drosophila melanogaster pico (21% identical), and 1 more. Paralogues in human: GRB14 (49% identical), GRB7 (48% identical), RAPH1 (29% identical), APBB1IP (24% identical).
Diseases named in the same sentence as GRB10 in open-access papers:
GRB10 is named in the same sentence as 94 diseases in open-access papers, as found by Europe PMC text mining. Sharing a sentence is not in itself a finding about the gene and the disease. The quoted sentences say what the papers report.
diabetes (14 papers, 2014 to 2024). "In this study, we aimed to investigate the association between GRB10 polymorphisms and susceptibility to type 2 diabetes mellitus (T2DM) vascular complications." (PMID 34651026, 2021). "Eight single nucleotide polymorphisms (SNPs) in the GRB10 gene were genotyped by MassARRAY system and 934 patients with type 2 diabetes mellitus (T2DM) were included for investigation." (PMID 34651026, 2021). "Although GRB10 is associated with both diabetes and vascular disease, the relationship between GRB10 gene polymorphism and diabetic cardiovascular disease had not been studied previously." (PMID 34651026, 2021). "Herein, we aimed to assess the therapeutic effect of catalpol on a mouse model diabetic nephropathy and the potential role of Grb10 in the pathogenesis of this diabetes-associated complication." (PMID 26986757, 2016). "Conversely, the overexpression of GRB10 in MIN6 cells induced β-cell dedifferentiation, indicating potential therapeutic targeting of GRB10 to address β-cell dysfunction in diabetes." (PMID 39057094, 2024). "We also examined the changes in Grb10 protein expression in mouse kidneys at 10 weeks following the induction of diabetes." (PMID 26986757, 2016). "Catalpol treatment could improve diabetes-associated impaired renal functions and ameliorate pathological changes in diabetic kidneys, while such beneficial effects correlate with a down-regulation of Grb10 expression and a concomitant up-regulation of IGF-1/IGF-1R signaling in diabetic kidneys." (PMID 26986757, 2016). "Growth factor receptor-bound protein 10 (Grb10), a suppressor of IGF1R pathway, has been shown to play a critical role in regulating diabetes-associated cognitive impairment." (PMID 25268761, 2014). "Collectively, this information indicates that GRB10 may be a key gene involved in the regulation of diabetes mellitus and related vascular complications." (PMID 34651026, 2021). "Also, a genome-wide analysis of the DNA methylation quantitative trait locus (mQTL) in human pancreatic islets revealed 383 CpGs (0.08% of tested CpGsites), showing significant associations including known diabetes loci, e.g., ADCY5, KCNJ11, HLA-DQA1, INS, PDX1 and GRB10." (PMID 38136971, 2023). "The results of Western blot validation showed that dynamic changes in proteins, such as IGF2, Ly6a, Grb10, and UBD, occurred to regulate the incidence of diabetes by influencing the insulin receptor substrate (IRS) signaling pathway." (PMID 30131712, 2018). "Additionally, numerous identified mQTL-SNPs cover previously identified GWAS loci for obesity, lipid and diabetes related traits e.g. POMC, GIPR, GRB10, FADS2, SORT1 and APOA5." (PMID 27322064, 2016). "Furthermore, GRB10, as a key downstream mediator of vascular smooth muscle cell (VSMC) miR-504 function, is closely related to vascular diseases under the conditions of diabetes mellitus." (PMID 34651026, 2021). "Since Grb10 has been demonstrated to negatively regulate IGF-1/IGF-1R signaling, we then determined whether catalpol-mediated down-regulation of Grb10 expression was coupled to up-regulation of IGF-1/IGF-1R signaling in diabetic kidneys." (PMID 26986757, 2016).
Insulin resistance (11 papers, 2014 to 2025). Increased resistance towards insulin, that is, diminished effectiveness of insulin in reducing blood glucose levels. "Overexpression of Grb10 caused postnatal insulin resistance." (PMID 31333621, 2019). "Conversely, transgenic mice overexpressing Grb10 exhibited impaired glucose tolerance and insulin resistance." (PMID 25551289, 2014). "Furthermore, overexpression of Grb10 inhibits the interaction of the insulin receptor with PI3K, thus reducing insulin signaling and causing insulin resistance." (PMID 36982168, 2023). "In addition, the fat-specific knockout of GRB10 was shown to inhibit lipolysis and thermogenic gene expression, reduce energy consumption, and aggravate diet-induced obesity and insulin resistance." (PMID 34651026, 2021). "mTORC1 hyperactivation can lead to insulin resistance through multiple mechanisms, including the phosphorylation of IRS-1 and the regulation of insulin signaling via Grb10." (PMID 40141237, 2025). "mTORC1 also regulates insulin signaling via Grb10 (growth factor receptor-bound protein 10), which inhibits threonine phosphorylation of insulin/IGF receptors and blocks PI3K/Akt signaling, thereby disrupting the IRS axis leading to insulin resistance and increased hyperglycemia." (PMID 37894760, 2023).
Obesity (10 papers, 2009 to 2025). Accumulation of substantial excess body fat. "Novel high impact variants resulting in premature stop codons were identified in the following genes associated with enriched obesity pathways in Meishan pigs: PLIN1 (adipogenesis, white adipose tissue browning), GRB10 (insulin receptor signaling), and ACOT4 (stearate biosynthesis I)." (PMID 40340757, 2025). "This interaction may have implications for targeting Grb10 in the treatment of obesity." (PMID 38027481, 2023). "In obesity, hyperactivation of mTORC1 induced by excessive nutrition and mitogens can lead to phosphorylation of insulin receptor substrate 1 (IRS-1) by S6K1 and negative regulation of insulin signaling by GRB10 (growth factor receptor bound protein 10)." (PMID 37511253, 2023).
type 2 diabetes (8 papers, 2008 to 2025). "Polymorphism in GRB10 has been associated with the risk of coronary heart disease in individuals with type 2 diabetes." (PMID 38904047, 2024). "Grb10 has been linked with human growth retardation and type 2 diabetes when upregulated or mutated, which alters Grb10 protein-protein interactions." (PMID 19166614, 2009). "Studies have also shown that disruption of Grb10 expression due to transcriptional and epigenetic changes can lead to type II diabetes." (PMID 39543691, 2024). "In this context, it has been shown that some SNPs in the GRB10 gene correlates indeed with type 2 diabetes in human." (PMID 19424485, 2008).
Silver-Russell syndrome (7 papers, 2013 to 2025). Silver-Russell syndrome is characterized by growth retardation with antenatal onset, characteristic facies and limb asymmetry. "GRB10 duplication has also been suggested as a genetic cause of Silver-Russell syndrome (MIM # 618905), a well-known short stature syndrome." (PMID 40577202, 2025). "Grb10, which is also called Meg1, is an imprinted gene on mouse proximal chromosome 11 and a candidate gene causing Silver-Russell syndrome." (PMID 28476045, 2017). "Diagnosed with Silver-Russell syndrome (SRS) using MS-MLPA, which revealed a normal copy number variant and hypermethylation of both GRB10 (7p12.1) and MEST (7q23.1) genes." (PMID 40730975, 2025). "In patients with Silver-Russell syndrome (SRS), one patient exhibited hypermethylation of the GRB10 and MEST genes, along with segmental uniparental disomy (UPD) on chromosome 7 (patient 1)." (PMID 40730975, 2025).
leukemia (6 papers, 2014 to 2023). A malignant (clonal) hematologic disorder, involving hematopoietic stem cells and characterized by the presence of primitive or atypical myeloid or lymphoid cells in the bone marrow and the blood. "Grb10 overexpression in an in vitro leukaemia model was associated with increased cell numbers in S-phase, increased proliferation and decreased apoptosis, suggesting that its role in cell cycle regulation is highly context dependent." (PMID 25551289, 2014). "One study showed that GRB10 is highly expressed in leukemia, and that the level of GRB10 expression is related to the survival of leukemia patients." (PMID 32235747, 2020). "Furthermore, molecular mechanism research showed that exo-circ-0009910 and intercellular circ-0009910 promote leukemia cell proliferation and cell cycle transition by up-regulating growth factor receptor-bound protein 10 (GRB10) via sponging miR-5193-3p." (PMID 37124518, 2023).
breast carcinoma (5 papers, 2013 to 2020). "Aberrant methylation and increased LOI of growth factor receptor-bound protein 10 (GRB10) are related to breast cancer." (PMID 32448196, 2020). "Four CpG sites located nearest the genes CTNNA2, GRB10, RPH3AL, and TINCR showed individual associations with breast cancer risk in a multivariable model (P < 0.05) and were also associated with breast cancer risk in matched case-control pairs in EPIC-Italy." (PMID 31039828, 2019). "In breast cancer and pancreatic cancer cohorts (GSE27567 and GSE49641 respectively), increased GRB10 level was found in peripheral blood myeloid cells from breast and pancreatic cancer patients compared with those from healthy control donors." (PMID 29973593, 2018).
prostate carcinoma (5 papers, 2015 to 2025). A carcinoma that arises from epithelial cells of the prostate gland. "In PDXs studying hormone-naive prostate cancer, the Growth Factor Receptor Bound Protein 10 (GRB10) gene was found to be the most significantly upregulated, showing increased expression during and before the development of castration resistant prostate cancer." (PMID 36358740, 2022). "Recently, it was shown that growth factor receptor-bound protein 10 (GRB10), has pro-proliferative function in prostate carcinoma, and that it sustains AR activity by interacting with PP2A." (PMID 33572160, 2021).
acute myeloid leukemia (4 papers, 2022 to 2024). Acute myeloid leukemia (AML) is a group of neoplasms arising from precursor cells committed to the myeloid cell-line differentiation. "For instance, the expression of GRB10 is upregulated in acute myeloid leukemia (AML), which is associated with increased cell cycle progression and cell proliferation." (PMID 35790975, 2022). "Exosomal circ_0009910 regulates proliferation, cell cycle, and apoptosis of acute myeloid leukemia cells by interfering with the miR-5195-3p/GRB10 axis." (PMID 38098508, 2023). "In acute myeloid leukemia, the expression of GRB10 is elevated, and overexpression of GRB10 in cells leads to abnormal cell proliferation." (PMID 37179120, 2023). "However, the tumor suppressive role of GRB10 has been elucidated in human acute myeloid leukemia." (PMID 39223679, 2024).
intrauterine growth restriction (4 papers, 2016 to 2025). "Because it is a key genetic component of developmental programming, recent studies have also suggested that placental GRB10 plays a role in regulating fetoplacental growth and that it is thereby implicated in the pathophysiology of fetal growth restriction in the context of fetal gender." (PMID 27370225, 2016).
lung carcinoma (4 papers, 2018 to 2022). "Based from the results, we have noted low specificities for certain genes and cancer types including GRB10 gene for lung cancer and GNAS gene for thyroid cancers." (PMID 32448196, 2020). "Further, more lung cancer patients with higher levels of all three molecules (GRB10, IRS1, and IGF1R) were in stage III/IV group than the stage I/II group." (PMID 29973593, 2018). "Based on the elevated BAE, MAE and TE signatures observed for various cancers over benign lesions, we formulated a statistical malignancy prediction model and identified GNAS, GRB10 and SNRPN as effective diagnostic biomarkers in ten different cancer types, including lung cancer." (PMID 34906185, 2021). "In addition, GRB10 levels in peripheral blood myeloid cells correlated with stages of human lung cancer (GSE20189), with stage III/IV lung cancer showing higher levels of GRB10 than stage I/II." (PMID 29973593, 2018). "A recent study identified aberrant allelic expression of both GNAS and HM13 at 20q11-13.32, as well as that of imprinted GRB10 at 7p12.1 and SNRPN 15q11.2 as useful biomarkers for lung cancer diagnosis." (PMID 36461044, 2022).
cervical cancer (3 papers, 2016 to 2024). A primary or metastatic malignant neoplasm involving the cervix. "Expression of GRB10 is upregulated in melanoma, cervical cancer and AML." (PMID 27977763, 2016).
coronary heart disease (3 papers, 2021 to 2025). "A recent study has shown that the rs1800504 polymorphism in the GRB10 gene is associated with blood lipids levels and, subsequently, the risk of coronary heart disease in patients with T2DM." (PMID 41614819, 2025). "We found that GRB10 rs1800504 CC+CT genotypes were significantly associated with increased risk of coronary heart disease (CHD) compared with TT genotype (OR = 2.24; 95%CI: 1.36–3.70, p = 0.002)." (PMID 34651026, 2021).
Hepatic steatosis (3 papers, 2021 to 2024). Steatosis is a term used to denote lipid accumulation within hepatocytes. "In at least two mouse models Grb10 expression has been linked with hepatic steatosis, a precursor of non-alcoholic fatty liver disease (NAFLD) and the most frequent cause of liver failure worldwide." (PMID 39343875, 2024). "It is therefore likely that the T2D-associated DNA methylation changes affecting GRB10 lead to its activation and hence promotion of hepatic steatosis and IR." (PMID 34046015, 2021). "Curiously, in different models of hepatic steatosis Grb10 expression is induced, including through exposure to cadmium during gestational development or post-natal exposure to tunicamycin or a high fat diet." (PMID 38816743, 2024). "Interestingly, more recent work in rodents has revealed an important axis between the activation of Grb10 and the promotion of hepatic steatosis." (PMID 34046015, 2021).
osteoarthritis (3 papers, 2020 to 2023). A noninflammatory degenerative joint disease occurring chiefly in older persons, characterized by degeneration of the articular cartilage, hypertrophy of bone at the margins and changes in the synovial membrane. "It has been shown that GRB10 and E2F3 can be used as diagnostic markers of osteoarthritis, and they are important in the occurrence and development of this condition." (PMID 36960385, 2023). "In conclusion, GRB10 and E2F3 can be used as diagnostic markers of osteoarthritis, and immune cell infiltration plays an important role in the occurrence and progression of OA." (PMID 32235747, 2020).
thyroid cancer (3 papers, 2020 to 2024). "It was found that GRB10 was up-regulated in cholangiocarcinoma, colon adenocarcinoma, head and neck squamous carcinoma, renal chromophobe, clear renal carcinoma, hepatocellular carcinoma, lung adenocarcinoma, lung squamous carcinoma, gastric adenocarcinoma and thyroid carcinoma." (PMID 37179120, 2023).
transient neonatal diabetes mellitus (3 papers, 2013 to 2024). Transient neonatal diabetes mellitus (TNDM) is a genetically heterogeneous form of neonatal diabetes (NDM) characterized by hyperglycemia presenting in the neonatal period that remits during infancy but recurs in later life in most patients. "Approximately half of transient neonatal diabetes mellitus (TNDM) patients with methylation disturbance at PLAGL1 have biallelic pathogenic variants in ZFP57, and have MLID involving LOM at PLAGL1, GRB10, and PEG3." (PMID 39090763, 2024).
clear cell renal cell carcinoma (2 papers, 2022 to 2024). "In support of a predominantly epithelial role, human GRB10 has been shown to be a tumour suppressor in clear cell renal cell carcinoma, a prevalent epithelial kidney cancer." (PMID 38816743, 2024).
Cognitive impairment (2 papers, 2014 to 2016). Abnormal cognition is characterized by deficits in thinking, reasoning, or remembering. "We have recently reported that a continuous hyperglycemia condition led to an increased expression of endogenous GRB10 in the hippocampus of rats with diabetic encephalopathy, which might cause damages to nerve function such as cognitive impairment." (PMID 25268761, 2014). "A previous study reported that endogenous GRB10 expression was increased in the hippocampus of rats with diabetic encephalopathy and that this increase might result in damaged nerve functions and cognitive impairments." (PMID 27370225, 2016).
congenital heart disease (2 papers, 2021 to 2024). A heart disease that is present at birth. "However, hypermethylation of the GRB10 ICR in peripheral blood samples has recently been associated with congenital heart disease." (PMID 34239874, 2021).